LAG3 (lymphocyte activating 3)
Diseases named in the same sentence as LAG3 in open-access papers (continued):
Sharing a sentence is not in itself a finding about the gene and the disease.
gastric cancer (continued). "In gastric cancer, the inhibitory ligands of LAG3, LSECtin, and MHC II are correlated with the expression of PD-L1, which may be indicative of the OS of patients with gastric cancer." (PMID 35111155, 2021). "LAG-3 expression has been demonstrated to be associated with reduced OS and DFS in hepatocellular carcinoma and in Epstein–Barr-virus-positive and MLH1-defective gastric cancer." (PMID 33803936, 2021). "Therefore, we analyzed the correlation between LAG3 expression levels and cholesterol score, aiming to preliminarily explore the relationship between cholesterol score and the immunotherapeutic outcomes in gastric cancer patients." (PMID 39777330, 2024). "This study aimed to analyze the spatial distribution of LAG3 + cells in relation to clinicopathological and survival data in a large set of 580 primary resected and neoadjuvantly treated gastric cancers (GC)." (PMID 37311986, 2023). "However, after surgery for gastric cancer, a positive correlation was found for LAG-3 upregulation with PD-1 expression on CD4+ and CD8+ T cells, which might be related to impaired cell-mediated immunity." (PMID 36077354, 2022). "Immunotherapy research in gastric cancer has focused on typical immune checkpoint pathways such as PD-1/PD-L1, CTLA-4, and LAG-3." (PMID 41228276, 2025). "Although expression of LAG-3 on T cells promotes T cell dysfunction, the soluble version of LAG-3 was a good prognostic marker in gastric cancer and positively correlated with CD8+ T cell frequency and secretion of IL-12 and IFN-γ in peripheral blood." (PMID 35708739, 2023). "Nonetheless, LAG3 was described as a poor prognostic factor in patients with EBV-positive and MLH1 defective gastric cancer." (PMID 37509517, 2023). "Other inhibitors or agonists of immune checkpoint molecules, including the inhibitors of CTLA4, LAG3, Tim3, and TIGIT, as well as the agonists of OX40, are currently in clinical trials in the treatment of gastric cancer." (PMID 36042469, 2022). "PD-1, TIM3, 2B4, and Lag3 are downregulated in CXCR5+CD8 T cells in colon cancer, but within gastric cancer PD-1, Lag3, CTLA4, and Tigit are upregulated." (PMID 36314014, 2022). "The immune checkpoint analysis indicated that gastric cancer patients with upregulated GGT5 expression showed a higher TIDE score and expression of CD274, CTLA4, HAVCR2, LAG3, PDCD1, PDCD1LG2, and TIGIT than patients in the GGT5-low expression group." (PMID 35368661, 2022). "Therefore, LAG3, a newly discovered immunosuppressive molecule, may be an important factor influencing the efficacy of gastric cancer immunotherapy, and anti-LAG3 inhibitors may have potential for developing novel immunotherapeutic strategies for the treatment of gastric cancer." (PMID 36042469, 2022). "Finally, an ongoing study with margetuximab combined with anti-PD-1 (retifanlimab) or anti-PD-1/LAG-3 (tebotelimab) ± chemotherapy in first-line therapy of advanced/metastatic HER2 + gastroesophageal junction (GEJ) or gastric cancer (GC) deserves mention." (PMID 34426663, 2021). "In gastric cancer, compared to CD68+ macrophages, higher expression of LAG3 can be found in CD3+/CD8+ T cells." (PMID 35111155, 2021). "In addition, therapeutic strategies targeting other molecules, such as CTLA4, LAG3, Tim3, TIGIT, and OX40, have also been developed to improve the treatment efficacy of gastric cancer immunotherapy." (PMID 36042469, 2022). "Studies on anti-LAG3 inhibitors in gastric cancer are currently in phase I/II clinical trials, without any published results." (PMID 36042469, 2022). "In exhausted T cells, these gene markers (PD1, CTLA4, LAG3, TIM3 and GZMB) were consistently significantly correlated with the expression of CLDN10, which further suggested that the expression level of CLDN10 in gastric cancer is related to immune infiltration." (PMID 34721537, 2021).
gastric cancer (continued). "In the NCI-N87 gastric cancer model, we observed once more that intratumoral B7H3.CAR EBVSTs upregulated PD-1 and TIM-3 but not LAG-3 expression, suggesting activation within tumor sites and robust antitumor activity." (PMID 38717140, 2024).
lung cancer (68 papers, 2016 to 2026). A malignant neoplasm involving the lung. "LAG-3 has been shown to be expressed in tumor-infiltrating lymphocytes in a variety of tumor types, including breast, ovarian, and lung cancers, and is commonly associated with increased numbers of PD-1+ T cells." (PMID 35601491, 2022). "Nonetheless, these BTLA+ lymphocytes, which are also PD-1+, TIM3+, CTLA-4+, and LAG-3+, seem to be terminally exhausted and poorly functional, and are associated to disease progression in lung cancer." (PMID 34532285, 2021). "SPECT/CT imaging of both probes showed specific in vivo tumor uptake in multiple lung cancer models, with significant linear correlation with ex vivo tumor uptake and immunohistochemical expression levels of LAG‐3/PD‐L1." (PMID 39513410, 2025). "High cytotoxic T cell infiltration generally correlates with increased OS in lung cancer, whereas cytotoxic TILs expressing immune inhibitory markers such as PD-1, TIM-3, and LAG-3 are associated with an exhausted immune phenotype and poor prognosis." (PMID 40524071, 2025). "The current strategy also allowed surveillance on LAG‐3 expression in lung cancers during immunotherapy." (PMID 39513410, 2025). "LAG-3 inhibitors are used in some cancers, such as head and neck cancer, lung cancer, and metastatic melanoma." (PMID 39770483, 2024). "The combination of CBL-B-specific small molecule inhibitors with anti-PD-1/anti-LAG-3 antibody immunotherapies resulted in significant therapeutic efficacies in lung cancer models resistant to conventional immunotherapies." (PMID 39030301, 2024). "This study establishes the feasibility and safety of dual targeting of PD-1 and LAG-3 before lung cancer surgery." (PMID 38689060, 2024). "The combination of CBL-B-specific small molecule inhibitors with anti-PD-1/anti-LAG-3 immunotherapies demonstrated notable therapeutic efficacy in models of lung cancer refractory to immunotherapies, overcoming PD-1/LAG-3 mediated resistance." (PMID 39030301, 2024). "PD-1/LAG-3 molecular mechanism of co-signaling was identified in T-cells, and combination of CBL-B inhibitors with anti-PD-1/anti-LAG-3 immunotherapies overcame PD-1/LAG-3-mediated resistance in models of lung cancer refractory to immunotherapies." (PMID 39030301, 2024). "Pharmacologic inhibition of CBL-B combined with PD-1/LAG-3 co-blockade demonstrated notable therapeutic efficacies in a lung cancer model poorly responsive to immunotherapies." (PMID 39030301, 2024). "These patients showed drastically reduced overall survival and their T-cells strongly co-upregulated PD-1 and LAG-3 following in vitro stimulation with human lung cancer A549-SC3 stimulator cells as described in." (PMID 39030301, 2024). "CBL-B inhibition combined with PD-1 and LAG-3 antibody-co-blockade more than tripled survival in mice with lung cancer poorly responsive to immunotherapies." (PMID 39030301, 2024). "Patients with head and neck (N = 2) or lung cancer (N = 4) were included in an imaging substudy of a phase 1 trial with BI 754091 (anti-PD-1) and BI 754111 (anti-LAG-3)." (PMID 36859619, 2023). "For example, the combination of anti-PD-1 with anti-TIM-3 has been used for lung cancer, and the combination of anti-LAG-3 and anti-PD-1 for mesothelioma and triple-negative breast cancer." (PMID 35037899, 2022). "LAG-3 expression has been described on lung cancer cell lines and fresh surgical lung cancer specimens using immunohistochemistry." (PMID 35265944, 2022). "Fourteen samples of benign lung tissue lesions were collected as the control group, and the expression levels of LAG‐3 in the lung cancer cells and tissue samples were measured via immunohistochemistry." (PMID 32077528, 2020). "To strengthen its usefulness in these respects, we measured the expression of LAG‐3 in lung cancer and further analyzed its clinical significance." (PMID 32077528, 2020).
lung cancer (continued). "T‐cell immunoglobulin and mucin‐domain containing 3 (TIM‐3), lymphocyte‐activation gene 3 (LAG‐3), and programmed cell death 1 (PD‐1) showed differential functional impact, tissue/cell distribution, and clinical significance in nonsmall cell lung cancer." (PMID 33135337, 2020). "The data on LAG‐3 expression in lung cancer in TCGA database were collected, and the relationship between LAG‐3 expression and survival was analyzed to generate a survival curve." (PMID 32077528, 2020). "Additionally, a noteworthy aspect of this study is the pioneering demonstration of simultaneous imaging of LAG‐3 and PD‐L1, a development that enables the distinction of diverse immunotypes in lung cancer models." (PMID 39513410, 2025). "Notably, late-stage lung cancer specimens were highly infiltrated with USP24+PD-1+Lag-3+CD8+ dysfunctional T cells, while USP24 and Tex markers were barely expressed in patients with early-stage lung cancer." (PMID 40238877, 2025). "LAG-3, a surface molecule belonging to the immunoglobulin superfamily, has been detected in tumor-infiltrating lymphocytes (TILs) in various cancer types, including breast, ovarian, and lung cancers." (PMID 38672108, 2024). "Whilst LAG-3 inhibition is an attractive therapeutic target in restoring T-cell function, we demonstrate genetically elevated LAG-3 levels as being associated with reduced CRC, endometrial and lung cancer." (PMID 38527997, 2024). "Indeed, co-expression of LAG-3 and PD-1 in peripheral blood T cells from patients with lung cancer are reported to be biomarkers for T cell dysfunction." (PMID 37841254, 2023). "Western blots showed that LAG‐3 was expressed in lung cancer cell lines." (PMID 32077528, 2020). "Therapeutic studies investigating the efficacy of LAG3 inhibition in EAC will also provide predictive evidence on the determination of the LAG3 expression in the tumour microenvironment, as we have learned in the past for the determination of PD-L1 in lung cancer." (PMID 32592066, 2020). "Additionally, the pioneering simultaneous imaging of LAG‐3 and PD‐L1 allows for distinguishing various lung cancer immunotypes, which is very valuable for improving the immunotherapeutic efficacy by properly selecting immune checkpoint inhibitors as well as their optimal intervention timing." (PMID 39513410, 2025). "In addition, the use of well-established immune checkpoint inhibitors, such as PD-1/PD-L1 blockers or LAG-3 antagonists, may hold enhanced therapeutic relevance in lung cancer patients exposed to high levels of air pollution." (PMID 41274118, 2025). "SPECT/CT imaging of lung cancers with 99mTc‐HYNIC‐αLAG‐3 and 99mTc‐HYNIC‐αPD‐L1 probes represents an effective method for noninvasively visualizing human LAG‐3 and PD‐L1, as well as immunotherapy resistance monitoring." (PMID 39513410, 2025). "The lung cancer model treated with NBTXR3 metal nanoparticles plus microwave irradiation, anti-PD-1, anti-TIGIT and anti-LAG-3 demonstrated increased efficacy compared to a protocol that excluded LAG-3 blockade." (PMID 40277786, 2025). "Drugs targeting checkpoints like LAG-3 and TIGIT, for example, are drawing considerable interest in lung cancer for their potential to enhance immune responses, either as single agents and/or in combination." (PMID 40524071, 2025). "Radiotherapy combined with NBTXR3 plus simultaneous blockade of three immune checkpoint receptors, PD1, LAG3 and TIGIT, was evaluated in an animal model of lung cancer resistant to anti-PD1 therapy." (PMID 40277786, 2025). "Further complicating the treatment landscape, resistance to PD-1 inhibitors in lung cancer has been correlated with upregulation of other immune checkpoints such as TIM-3 and LAG-3 in mouse models." (PMID 39726592, 2024). "Clinical trials are ongoing to investigate the efficacy of targeting LAG3, TIM-3, and TIGIT in lung cancer." (PMID 38474400, 2024).
lung cancer (continued). "Prostate cancer, lung cancer, and ccRCC have all been studied using monoclonal antibodies that target different immune checkpoint inhibitors (such as CTLA4, PDCD1, and LAG3)." (PMID 39014265, 2024). "We combined NBTXR3-enhanced localized radiation with the simultaneous blockade of three different checkpoint receptors: PD1, LAG3, and TIGIT, and tested the treatment efficacy in an anti-PD1-resistant lung cancer model in mice." (PMID 36123677, 2022). "Again, many of the immune-modulatory genes differentially expressed in the mouse model were site-specifically recapitulated, e.g., higher CCL2, CXCL5, CXCL9, CXCL11, CXCL14, CXCL17, and IDO1 in lung cancers and higher CXCL12, FGL1, and LAG3 in liver cancers." (PMID 33985562, 2021). "In the context of acquired resistance to immunotherapy, CD8+ T cells in lung cancer often display elevated expression of multiple inhibitory receptors, such as PD-1, T cell immunoglobulin and mucin-domain containing-3(TIM-3), and Lymphocyte activation gene-3(LAG-3)." (PMID 41268560, 2025). "At the same time, Tregs expressing the lymphocyte-activation gene 3 (LAG-3) are more active in lung cancers than those not expressing it." (PMID 40136652, 2025). "Of note, PD1 expression was lower than LAG3 and TIGIT in CD8+ T cells, suggesting that LAG3 and TIGIT might be potential targets for alternative immunotherapies in lung cancer CNSm." (PMID 40883281, 2025). "T cells that express both LAG-3 and PD-1 exhibit a greater degree of exhaustion than those expressing PD-1 alone, making LAG-3 a potential target for rescuing dysfunctional T cells in lung cancer." (PMID 39726592, 2024). "PD-1/LAG-3 co-blockade inhibited CBL-B expression, while the use of a bispecific drug in clinical development also repressed C-CBL expression, which reverted T-cell dysfunctionality in lung cancer patients resistant to PD-L1/PD-1 blockade." (PMID 39030301, 2024). "Clinical trials of immune checkpoint modulators (TIM3, LAG-3, TIGIT, BTLA, and IDO) in lung cancer." (PMID 39726592, 2024). "A flow cytometric analysis in lung cancer samples revealed that BTLA expressing tumor infiltrating CD8 positive T-cells also showed increased expression of the checkpoint receptors PD1, CTLA4, LAG-3 and TIM-3." (PMID 38928307, 2024). "Cancers with high tumor-infiltrating lymphocytes (e.g., lung cancers) had high expression of immune-oncology markers, such as PD-L1, TIM3, FOXP3, PD-1, CTLA4, and LAG3 in TMA EdgeSeq and TCGA RNA-seq; this was also observed in normal hematopoietic tissues with TMA EdgeSeq." (PMID 36137139, 2022). "A study showed that using IL-12 to boost the cytotoxicity of NK cells in a lung cancer model (BALB/c mice injected with 4T1 cells) increased the NK cell population expressing high levels of coinhibitory molecules, including LAG-3, which limited NK cell-mediated antimetastatic activity." (PMID 31681269, 2019). "Such as in nonsmall cell lung cancer (NSCLC) as well as hepatocellular carcinoma (HCC), a malfunction CD8 + T cell population was discovered to be positively related to high levels of expression of suppressor receptor genes (PD1, PD-L1, LAG3, CTLA4, TIGIT, and HAVCR2)." (PMID 35845137, 2022). "In addition, the expression levels of inhibitory receptors such as T-cell immunoglobulin and mucin-domain containing-3 (TIM-3), lymphocyte-activation gene 3 (LAG-3), PD-1, and CTLA-4 in CD4+ or CD8+ T cells can be applied to predict the response to lung cancer immunotherapy." (PMID 30999966, 2019). "Meanwhile, neither EBV strain can effectively induce LAG3 and BTLA expression in lung cancer cells, suggesting that these molecules were mainly expressed within the infiltrating immune cells in the tumor tissue." (PMID 31159203, 2019).
metastatic melanoma (67 papers, 2018 to 2026). A melanoma that has spread from its primary site to another anatomic site. "Importantly, an analogous reprogrammed Treg state was associated with response to anti‐PD1 + anti‐LAG3 and longer overall survival in patients with metastatic melanoma." (PMID 40517319, 2025). "We present the case of an 81-year-old male with a history of recurrent metastatic melanoma previously treated with nivolumab and relatlimab (Opdualag), who developed a persistent pruritic eruption following initiation of dual PD-1/LAG-3 blockade." (PMID 41458837, 2025). "Current cornerstone treatments for metastatic melanoma include immune checkpoint modulators, such as LAG3 inhibitors, pembrolizumab, nivolumab, and ipilimumab targeting CTLA-4, and PDL1." (PMID 39974235, 2025). "In 2022, the U.S. Food and Drug Administration approved a novel dual immunotherapy of relatlimab, a lymphocyte activation gene-3 (LAG-3) inhibitor in combination with nivolumab for patients with unresectable or metastatic melanoma." (PMID 41476983, 2025). "Given the RELATIVITY-047 clinical trial findings, the FDA recently approved using relatlimab, a medication targeting lymphocyte-activation gene 3 (LAG-3), with nivolumab to treat unresectable or metastatic melanoma." (PMID 40075727, 2025). "Based on the RELATIVITY-047 trial, first combination strategies for PD-1 (nivolumab) and LAG-3 (relatlimab) targeting have been approved by the FDA for the treatment of unresectable or metastatic melanoma." (PMID 40148963, 2025). "Based on the results of RELATIVITY‐047, the immunotherapy regimen of relatlimab (a LAG‐3 inhibitor) in combination with Nivolumab was approved by the US FDA in March 2022 for the treatment of unresectable or metastatic melanoma." (PMID 40787068, 2025). "Despite suboptimal outcomes with monotherapy, the combination of relatlimab (LAG‐3 inhibitor) and nivolumab (Opdualag) was approved for the management of unresectable or metastatic melanoma in 2022, marking a significant milestone." (PMID 40787068, 2025). "A combination of LAG‐3 and PD‐1 antibodies has already been approved for the treatment of metastatic melanoma." (PMID 39560030, 2024). "Recently, the FDA officially approved an anti-LAG3 mAb (relatlimab) in combination with nivolumab for the treatment of metastatic melanoma, which is the world first approved LAG3 antibody drug." (PMID 38241591, 2024). "Very recently, an anti-lymphocyte-activation gene 3 (LAG3) antibody has also been approved for the treatment of patients with metastatic melanoma in the first-line setting." (PMID 38612803, 2024). "As the first FDA-approved LAG-3 inhibitor for metastatic melanoma treatment, Relatlimab represents a significant advancement in immunotherapy." (PMID 39743998, 2024). "A combination of anti-LAG-3 and anti-PD-1 is approved for the treatment of unresectable or metastatic melanoma in individuals aged 12 and older." (PMID 39273224, 2024). "Several LAG-3 targeting inhibitors in clinical trials and the combination of relatlimab (anti-LAG-3) and nivolumab (anti-PD-1) have been approved for treating - unresectable or metastatic melanoma." (PMID 39252941, 2024). "Currently, a few clinical trials are investigating LAG-3 inhibitors in people, and recently, the LAG-3 inhibitor relatlimab has been approved in combination with nivolumab for patients with metastatic melanoma." (PMID 38893123, 2024). "LAG-3 immunohistochemistry (clone D2G4O) was performed on pre-treatment formalin-fixed, paraffin-embedded metastatic melanoma specimens from 53 patients treated with combination anti-LAG-3 + anti-PD-1-based therapies." (PMID 37808404, 2023). "Our findings add to current ongoing investigations to identify biomarkers of response to the recently approved anti-LAG-3 combination immunotherapy in metastatic melanoma." (PMID 37808404, 2023).